CXCR4 (C-X-C motif chemokine receptor 4)
Diseases named in the same sentence as CXCR4 in open-access papers (continued):
Sharing a sentence is not in itself a finding about the gene and the disease.
infection (continued). "The ability of amino acid shifts to mediate crucial transitions in viral ontogeny within the host has previously been observed with chemokine receptor tropism: early viruses are almost exclusively CCR5-tropic and CXCR4 tropism arises later in infection." (PMID 21876761, 2011). "The infected U87.CD4.CXCR4 cells were harvested at day 5 post-infection, and HIV-1 DNA were extracted for PCR amplification employing subtype-specific oligonucleotide primers to detect, amplify, and quantify env recombinants in HIV-1 dual infections." (PMID 21232148, 2011). "In ~50% of HIV-1 subtype-B infected individuals, the coreceptor usage of the virus changes from a preference for CCR5 to a preference for CXCR4 over the course of infection." (PMID 21284906, 2011). "Use of CCR5 is frequently associated with the early stages of infection while progression of human immunodeficiency virus infection to AIDS and death is related to a viral tropism switch to CXCR4." (PMID 21789236, 2011). "It is possible that partial down regulations of both CD4 and CXCR4 result in a synergistic effect to achieve the potent inhibition of NL4-3 infection of MT4 cells." (PMID 22039528, 2011). "HIV-1 variants present early in the course of infection mainly use the coreceptor CCR5, while virus variants that use CXCR4 can appear later in infection." (PMID 21731496, 2011). "Several reports indicate that CXCR4 is down-regulated in primary B cells upon infection by EBV and this was confirmed by our qRT-PCR time-course analysis during infection with type 1 and type 2 EBNA-2 recombinant viruses." (PMID 21857817, 2011). "Our group showed that CD4+ thymocytes are depleted in large areas of the RAG-hu thymus following infection by CXCR4-tropic virus by immuno-staining." (PMID 21835012, 2011). "Because CXCR4 is the infection receptor for the CD4-indepndent infection of the mNDK vector, cell surface expressions of CXCR4 in these cells were analyzed." (PMID 21541353, 2011). "Pure R5 variants remain present after the appearance of CXCR4-using variants, and in the vast majority of HIV-infected individuals both virus populations co-exist during the remaining course of infection." (PMID 21731496, 2011). "In TE671 cells, the Eps15-DN rather enhanced the CD4-dependent HIV-1 vector infection provably due to elevated expression of CXCR4." (PMID 21541353, 2011). "Peak viremia typically occurs in the range of 1-2 months post-infection; however, CD4+ T cell loss in the blood is more severe with CXCR4 virus and the decrease in target cells is accompanied by a decrease in viremia." (PMID 21835012, 2011). "In the setting of prevention trials, the blocking of CCR5 should prevent infection and the initiation of the long and difficult evolution to CXCR4 use." (PMID 21760945, 2011). "The CXCR4 antagonist AMD3100 was added to the culture medium 2 hours post-infection to block re-infection of the cells." (PMID 22072966, 2011). "We have shown that HIV-1 infection in RAG-hu mice can be sustained for over a year post-infection with either CCR5 tropic or CXCR4 tropic virus." (PMID 21835012, 2011). "We first tested our 3 different anti-CXCR4 mAb clones (A145, A120 and A80) for their potential to inhibit the infection of the prototype X4 HIV-1NL4-3 and for purposes of controlling the prototype R5 HIV-1JR-FL in in vitro activated primary PBMC cultures." (PMID 22018245, 2011). "The majority of CRF14_BG isolates from Spain also use CXCR4, even those obtained from patients at early stages of infection." (PMID 21969855, 2011). "In our infection experiments CXCR4 was effectively repressed in both type 1 and type 2 EBNA-2-virus infected cells by the day 8 time-point." (PMID 21857817, 2011). "A neutralizing TNF-α antibody, infliximab (4 μg/ml, Sigma), was then used to treat MKN45 and HGC27 cells after an infection by 26695, and the induction of CXCR4 was inhibited significantly (P < 0.01, respectively)." (PMID 20699000, 2010).
infection (continued). "Human immunodeficiency virus type-1 (HIV) envelope protein binds to the CD4 receptor and to chemokine coreceptors CCR5 or CXCR4, leading to infection and destruction of the CD4-bearing immune cells: T lymphocytes and macrophages." (PMID 21179547, 2010). "As all strains of FIV examined to date use CXCR4 as the co-receptor for infection, an R5 to ×4 shift analogous to that observed in HIV infection cannot be invoked." (PMID 20420700, 2010). "When a comparison was done at an earlier stage of HIV-1 infection (CD4 counts > 200), CXCR4 use was more frequent among patients with subtype D infection, probably due to an earlier coreceptor switch than in patients infected with subtype A." (PMID 20307309, 2010). "Infection on NP2/CD4/CXCR4 is 60X (MCN) and 200X (MCR) greater than on the restricted HeLa/CD4 cells." (PMID 20929586, 2010). "CXCR4 has been implicated in different types of cancer, in the WHIM (Warts, Hypogammaglobulinemia, Infection and Myelokathexis) syndrome, in rheumatoid arthritis, and in the immune response during fungal asthma." (PMID 20967243, 2010). "With disease progression, variants would emerge that have a less complex, low affinity interaction with CD134 and a propensity for CD134-independent infection through a direct interaction with CXCR4." (PMID 20420700, 2010). "Masking the CD4 and V3 loop area by mHSA was also efficient for the blockade of CCR5-specific infection, but 3 times higher levels were necessary compared to the neutralization of CXCR4-viruses." (PMID 20525179, 2010). "The bicyclam AMD3100 is a small molecule (molecular weight 830 Da) that specifically binds CXCR4 and inhibits the infection of HIV-1 isolates that utilize CXCR4 as the receptor." (PMID 20967243, 2010). "In 50% of progressing HIV-1 patients, CXCR4-tropic (X4) virus emerges late in infection, often overtaking CCR5-tropic (R5) virus as the dominant viral strain." (PMID 19680436, 2009). "Subject 07 was infected with a subtype C virus, the others with subtype B; subtype C infections infrequently exhibit a CXCR4-using phenotype." (PMID 19479085, 2009). "In early infection CCR5-using viruses (R5 viruses) are mostly dominant while a receptor switch towards CXCR4 occurs in about 50% of the infected individuals (X4 viruses) which is associated with a progression of the disease." (PMID 19948048, 2009). "The actual incidence of CXCR4 using subtype C strains in natural infection, the time of their appearance in the disease progression and the relevance of their emergence have not been elucidated." (PMID 18328091, 2008). "Infection of human T-lymphoblastoid cell line RH9 with HIV-1 resulted in down-regulation of cell surface CXCR4 expression." (PMID 18190699, 2008). "Blocking coreceptor CXCR4 with either a small molecule, AMD3100 or an anti-CXCR4 mAb 12G5 also abrogated trans infection of the TZM-bl cells." (PMID 18414664, 2008). "At 4 days after infection cells were labeled with the CXCR4 12G5 MAb, followed by a FITC-conjugated secondary antibody and analyzed by indirect immunofluorescence microscopy." (PMID 18190699, 2008). "In an attempt to identify the step in viral replication controlled by CXCR4 signaling, the authors analyzed the early steps of infection, starting from fusion to integration." (PMID 18808680, 2008). "CD134-independent FIV infection is mediated by a direct interaction with CXCR4, analogous to infection with CD4-independent strains of HIV." (PMID 18721458, 2008). "In contrast, SHIVDH12R or SHIVKU1 use CXCR4 for infection, which is preferentially expressed on naïve CD4+ T cells." (PMID 18928523, 2008). "Although Subtype C predominantly uses CCR5, several instances of co-receptor switch to CXCR4 or even dual tropism have been observed in Subtype C, especially later in infection." (PMID 18489743, 2008).
infection (continued). "Perhaps in concert with protection of harbored virus, we also showed that P. gingivalis-mediated upregulation of CCR5 in TERT-2 cells increases the effectiveness of trans infection to permissive TZM-bl cells (CD4+ CXCR4+ CCR5+)." (PMID 18371227, 2008). "SPL 7013 is a polylysine based polyanionic dendrimer with naphthalene disulfonic acid surface groups that when formulated as a 5% gel protected 6 of 6 pigtailed macaques from infection with the predominantly CXCR4 tropic SHIV 89.6." (PMID 19094217, 2008). "In humans, the key coreceptors utilized by HIV are CCR5 and CXCR4, even though numerous other chemokine receptors appear to support infection in vitro." (PMID 19094217, 2008). "CXCR4 was shown to be selectively down-regulated from the cell surface by HIV-2/vcp in the context of CD4-independent infection or from cells infected with CD4-independent HIV-1 isolate that enters directly via CXCR4." (PMID 18190699, 2008). "Given that the HIV-1 NL4-3 virus used for infection is CXCR4-tropic, these results indicate that signaling from the CXCR4 receptor, but not from CD4, is critical for the ability of HIV to establish latent infection of non-activated T cells." (PMID 18808680, 2008). "Viral isolates capable of using CXCR4 emerge in nearly half the infections of subtype B towards the advanced stages of the disease." (PMID 18328091, 2008). "In contrast, ectopic expression of feCD134 ("endog.") enhanced infection of the control with all viruses (>10-fold) suggesting that sufficient endogenous CXCR4 is present to facilitate viral entry in the presence of native primary receptor." (PMID 18721458, 2008). "Infection of cells expressing CCR5/CXCR4 chimeric receptors revealed that SIVsm used the CCR5 receptor in a different mode than HIV-1." (PMID 17645788, 2007). "Despite expressing high levels of CCR5, TEMRA cells were strikingly resistant to infection with CCR5 (R5)–tropic HIV-1, but remained highly susceptible to CXCR4 (X4)–tropic HIV-1." (PMID 17465678, 2007). "By contrast, HIV-1 isolates that use CXCR4 (X4 viruses) commonly emerge in infected individuals at later stages of infection." (PMID 17684570, 2007). "The frequency of recombination catalyzed by Taq was < 0.005%/Kbp, or at least 100-fold less than that generated in dual infections of U87.CD4.CXCR4 cells." (PMID 17164002, 2006). "Susceptibility to in vitro infection of unstimulated peripheral blood mononuclear cells, prior of PHA activation, was decreased in EUs compared to UCs, either using a CXCR4-tropic or a CCR5-tropic HIV-1 strain (p = 0.02 and p = 0.05, respectively)." (PMID 16792805, 2006). "Down regulation of the major HIV-1 coreceptors CXCR4 and CCR5 in virus susceptible cells is a promising approach to prevent viral entry and establishment of productive infection." (PMID 16109172, 2005). "Widespread up-regulation of CXCR4 in T cells appears to be a common feature of severe infection." (PMID 41004596, 2025). "We therefore used the CXCR4-tropic HIV-1 strain in the following infection experiments." (PMID 39354676, 2025). "To test this hypothesis, we knocked out CPSF5 in primary CD4+ T cells using 2 independent guide RNA in 3 independent donors and conducted HIV-1 spreading infection assays as before alongside NT, CXCR4 knock-out, and CYPA knock-out controls." (PMID 41385587, 2025). "Patients with severe infection show elevated CXCR4 expression in neutrophils." (PMID 40227198, 2025). "Knock-out of CXCR4 ablated CXCR4-tropic NL4.3 strain infection as expected." (PMID 39259751, 2024). "Consistently, mavorixafor, an oral CXCR4 antagonist, increases the absolute number of lymphocytes and may improve the infection rate in WHIM, but the specific effect on the humoral response is not known at present." (PMID 38519141, 2024).
infection (continued). "HIV-1 initially targets CCR5-expressing tissue memory CD4+ T cells, and in the absence of early cART initiation, a co-receptor switch may occur, leading to the infection of naïve and memory CXCR4-expressing CD4+ T cells." (PMID 38787201, 2024). "After entering the human body, HIV infects cells by utilizing CD4 and CCR5/CXCR4 as primary and secondary receptors, respectively, leading to infection in its primary target cells such as T cells, macrophages, and dendritic cells, thereby establishing a long-term infection." (PMID 38785555, 2024). "Further, while transfection of a CXCR4-expressing plasmid increased susceptibility of JunB KO 1–6 cells to X4-tropic infection as compared to the empty vector control, it did not alter the susceptibility of these cells to R5-tropic, or VSV-G pseudotyped virus." (PMID 38835488, 2024). "As recently reported by the authors, when the infection was conducted using pseudotyped HIV incorporating the glycoprotein G from vesicular stomatitis virus (VSV-G) in a CD4/CXCR4/CCR5-independent manner, it was demonstrated that LX-2 cells exhibit permissiveness to intracellular HIV replication." (PMID 38715844, 2024). "For participants 1 and 2, coreceptor usage shifted from CXCR4-using to CCR5-using during untreated infection (participant 1’s shift was previously documented), while participant 4 had a minority CXCR4-using population in early infection that steadily became more dominant." (PMID 38214547, 2024). "Lastly, the expression of HIV coreceptors CCR5 and CXCR4 remained stable throughout infection." (PMID 38420260, 2023). "On the other hand, the expressions of CCR7 and CXCR4 were significantly induced by WT infection." (PMID 37513744, 2023). "CCR5-using viral strains predominate in the early phase of infection, while CXCR4-using viruses may emerge later in patients and are associated with increased pathogenicity of infection." (PMID 36770826, 2023). "At the same time, simultaneous knockout of both HIV co-receptors Chemokine C-C-Motif Receptor 5 (CCR5) and CXCR4 leads to a decrease in the expression of CCR5 and CXCR4, which makes the modified cells resistant to infection with R5 and X4 tropic viruses, even when using double tropic viruses." (PMID 38003266, 2023). "Because participants who donated blood for experiments #1 and #2 were different, it was possible to evaluate the effect of biological variation on the biomarkers of latency identified from the two sets of three 10-day models established with CXCR4-tropic infection in the two independent experiments." (PMID 38156317, 2023). "Additionally, we reported that AMD3100 or CXCL12 (the CXCR4 natural ligand) fully inhibited infection of primary CD4+ T cells by cell-free X4-1 Env-pseudotyped viruses (, and here)." (PMID 35622876, 2022). "High Cxcr4 expression indicated that CXCR4high MKs might migrate between the bone marrow microenvironment and circulation in response to infection." (PMID 35904250, 2022). "Most of the mutations did not impact the ability of MX2 to inhibit infection as measured by challenging U87-MG CD4/CXCR4 cells with a GFP-encoding HIV-1-based vector (HIV-1/GFP) and enumerating the number of GFP-positive cells at 48 h." (PMID 35880880, 2022). "Similar observations were seen in CCR5-tropic infection as in CXCR4-tropic infection." (PMID 36420277, 2022). "However, in our primary infection, CXCR4 expression was downregulated in infected PBMCs and upregulated in NOKs, albeit at a low level." (PMID 36272970, 2022). "Consequently, Th17 cells are permissive in vitro to infection by viruses that have R5 (CCR5) or X4 (CXCR4) tropism." (PMID 35197986, 2022). "GPI-FluIgG03-transduced TZM-bl cells were highly susceptible to infection with the HIV-1 strains including five CCR5-tropic viruses (JR-CSF, RHPA.c/2635, THRO.c/2626, CH077.t/2627, and MJ4), two CXCR4-tropic viruses (NL4-3 and LAI.2), and one dual-tropic virus (89.6)." (PMID 34821542, 2022).
infection (continued). "Proper timing of CXCR4 inhibition in the treatment of PTL may need to include reversal after control of infection, thus reactivating recruitment of progenitor cells involved in tissue repair." (PMID 35318804, 2022). "Additionally, co-ligation of a chemokine receptor, CCR5 or CXCR4, is needed to establish successful infection." (PMID 36230931, 2022). "Thus, the CXCL12/CXCR4 axis presents an excellent target for preventing infection and inflammation‐related PTL." (PMID 35318804, 2022). "Thus, the CXCL12/CXCR4 axis presents a promising target for preventing infection and inflammation‐related PTL." (PMID 35318804, 2022). "Using a large panel of viruses expressing primary Envs with CCR5 and/or CXCR4 usage and from different stages of infection, we show that all viruses can be transferred from infected T cells to MΦ ultimately leading to the formation of productively infected MGCs." (PMID 35622876, 2022). "Here, we investigated the capacity of viruses expressing primary envelope glycoproteins (Envs) with CCR5 and/or CXCR4 usage from different stages of infection, including transmitted/founder Envs, to infect MΦ by a cell-free mode and through cell-to-cell transfer from infected CD4+ T cells." (PMID 35622876, 2022). "The fact that extensive viral evolution correlates with the highest levels of naive infection argues that CXCR4-tropic and dual-tropic HIV viruses may be responsible for the majority of naive infection in our CPs." (PMID 34228640, 2021). "Control antibody GPI-FluIgG03-transduced TZM-bl cells were highly susceptible to infection with the eight HIV-1 isolates including five CCR5-tropic viruses (JR-CSF, RHPA.c/2635, THRO.c/2626, CH077.t/2627, and MJ4), two CXCR4-tropic viruses (NL4-3 and LAI.2), and one dual-tropic virus (89.6)." (PMID 33462383, 2021). "The expression of both CCR7 and CXCR4 increased significantly between 1.5 and 9 months post-infection for T cells specific for all three epitopes (p = 0.0002 and p = 0.0137, respectively), while the expression of CXCR3 remained stable between these two timepoints." (PMID 34960178, 2021). "We used this strategy to modify TZM cells and generate a cell line that was resistant to CCR5 tropic viruses while permitting infection of CXCR4 tropic viruses which could be controlled via treatment with Ganciclovir." (PMID 33516234, 2021). "However, if CD4 expression was the limiting factor for HIV infection in this setting, differential infection rates between T-PBMCs and T-Pure cells when exposed to CXCR4-tropic HIV would be expected." (PMID 34899645, 2021). "Notably, our data reporting sensitivity of HIV-1 to IFITM1 is supported by previous studies that also observed IFITM1 inhibition of infection/fusion using replication-competent CXCR4-tropic HIV-1 (42, –44, 47)." (PMID 34001619, 2021). "Use of CXCR4 is now generally associated with later stages of infection rather than a specific cell type." (PMID 34429135, 2021). "Further, we were able to confirm actual infection of subsets through detection of viral DNA in co-cultivated subsets singly positive for CXCR4, integrin β7, and dually positive for both CCR5/CXCR4 and β7/CCR5 by amplifying the C2V3 region of the env gene with β-actin serving as housekeeping control." (PMID 33816339, 2021). "To confirm that CXCL12-resistant (RES) HIV variants are present at an advanced stage of infection, we next measured the effects of CXCL12 on CXCR4-using, recombinant viral populations generated from plasma of nine late diagnosed individuals with CD4TL count < 200/μl." (PMID 33872329, 2021). "The CXCR4 envelope HIV-1NL4-3-Luc-pseudotyped virus was used for infection." (PMID 34076481, 2021). "The third, M-tropic HIV, can use CCR5, CXCR4 or both coreceptors, and arises in some individuals late in infection and in T cell-depleted environments such as in advanced HIV-1 disease, in the central nervous system, or in settings of experimental depletion of CD4+ T cells." (PMID 33594125, 2021).